RIF1 (replication timing regulatory factor 1)
Diseases named in the same sentence as RIF1 in open-access papers (continued):
Sharing a sentence is not in itself a finding about the gene and the disease.
cancer (26 papers, 2015 to 2025). A tumor composed of atypical neoplastic, often pleomorphic cells that invade other tissues. "Here, we investigate changes in expression level and splicing of transcripts encoding RIF1, an important genome stability regulator that coordinates DNA replication and repair, whose expression has been reported to be derailed in cancer." (PMID 40806439, 2025). "Rap1 Interacting Factor 1 (RIF1) plays a crucial role in genome stability and is implicated in cancer pathogenesis." (PMID 40806439, 2025). "Exposure to DNA damage inhibited Ex32 splice-in, potentiated the association of SRSF3 and SRSF7 with RIF1 pre-mRNA, and caused an increase in RIF1-S protein expression, which was also observed across a diverse set of primary cancers." (PMID 41489901, 2025). "As impaired RT, DSBR and fork reactivation are associated with genomic instability, a hallmark of malignant transformation, RIF1 has a diagnostic, prognostic, and therapeutic potential in cancer." (PMID 34768871, 2021). "BRCA2, BLM, ERCC2, RECQL, REV3L and RIF1 were among the most promising candidates, with some of them previously associated with predisposition syndromes to other cancers." (PMID 30871259, 2019). "We also observed that the RIF1 expression level was significantly associated with clinical stage (P < 0.05) and inversely correlated with the differentiation state of the cancer cells (P < 0.05)." (PMID 30237512, 2018). "Analysis of alternatively spliced transcripts in patient-matched normal and cancer samples revealed a shift towards exclusion of RIF1 Exon 31 and expression of the RIF1-S splice variant in several cancers, including breast, colon, lung, liver, and prostate cancer." (PMID 40806439, 2025). "On the other hand, cancers with RIF1 mutations could be more responsive to chemotherapeutic regimens." (PMID 31337767, 2019). "Based on the data presented here, we envision that 53BP1 hypo-phosphorylation and the associated failure of RIF1 recruitment may emerge as novel indicators for PARPi resistance in BRCA1-deficient cancers." (PMID 27494840, 2016). "RIF1 may promote cancer progression by binding to the promoter of the human telomerase reverse transcriptase gene encoding the catalytic subunit of telomerase, an enzyme essential for cancer transformation in many tumors." (PMID 34768871, 2021). "RIF1 overexpression has been reported in several cancer types, including breast, ovarian, cervical, and non-small cell lung cancer (NSCLC)." (PMID 40806439, 2025). "Here, we use RIF1 mRNA expression data from TCGA to investigate total RIF1 expression in a larger number of cancer types, selected based on availability of matched normal samples." (PMID 40806439, 2025). "We considered how well the observed changes in RIF1 splicing conform to these general patterns for the four cancer subtypes." (PMID 40806439, 2025). "For LumA, LumB, and HER2E cancers, RIF1 Exon 31 is within the grouping of Cancer-Altered Short exons showing increased exclusion, given that it has a ΔPSIav less than −0.1 in each of these cancer subtypes (−0.132, −0.155, and −0.161, respectively)." (PMID 40806439, 2025). "In other words, RIF1 Exon 31 is behaving ‘typically’ for Cancer-Altered Short exons in being more often excluded in these receptor-positive cancer subtypes." (PMID 40806439, 2025). "MAD2L2 is implicated in response to DNA damage, potentially acting downstream of RIF1, contributing to genomic instability, a critical factor in cancer initiation." (PMID 38167649, 2024). "There is mounting evidence that there is a link between telomeres and the RIF1 protein and the proliferation of cancer cells." (PMID 37548940, 2024). "Restoration of HR repair capacity in BRCA1/2 mutant cancer cells due to the disruption of DNA end-resection blockers such as 53BP1 and RIF1; ii." (PMID 37415733, 2023).
cancer (continued). "Regaining HR and fork protection by inactivation of 53BP1, RIF1, REV7, or a Shieldin, and PTIP, respectively, results in resistance to PARPi in BRCA1-deficient cancer cells." (PMID 33784323, 2021). "As olaparib, a PARP1 inhibitor, is widely used in cancer therapy, RIF1 can be considered a prognostic marker in olaparib-based anti-cancer treatment." (PMID 34768871, 2021). "As DNA repair is critical for genomic stability and cancer transformation, RIF1 can be considered as an anti-apoptotic factor and target in anti-cancer treatment." (PMID 34768871, 2021). "Suppressor of cancer cell invasion (SCAI) competes with replication timing regulatory factor 1 (RIF1) for the phosphorylated 53BP1." (PMID 32570875, 2020). "Recently, it was disclosed that WIP1 dephosphorylated 53BP1 at Threonine 543 and attenuated its interaction with RIF1, leading to decreased sensitivity of cancer cells to PARPi, which confirmed the importance of the interaction between 5BP1 and RIF1 once more." (PMID 32563252, 2020). "Overall, considering the multifunctional nature of Rif1 and its connection with some diseases including cancer, the design and set up of a platform for full-length Rif1 expression or each of its domain seems to be necessitated." (PMID 30218996, 2018). "We are trying to mutate the PP1 interaction motif of RIF1 expression plasmid and we would continue to explore the role of RIF1 in DNA replication time regulation in human cancer cells in the future." (PMID 30237512, 2018). "To further confirm the correlation between RIF1 and hTERT, we evaluated RIF1 and hTERT protein expression level in cancer tissue samples from 75 EOC patients via IHC." (PMID 30075819, 2018). "Taken together, our data indicated that RIF1 promoted cancer stem cell-like properties of EOC cells." (PMID 30075819, 2018). "This second role of Rif1 has interesting implications for the use of DDK inhibitors as anti-cancer agents." (PMID 28273463, 2017). "RIF1 has been illustrated to play a significant role in DNA repair and DNA replication regulation pathway, but little is known about the role of RIF1 in cancer development and chemotherapy response." (PMID 29291010, 2017). "It is therefore important to understand RIF1 expression changes in cancer." (PMID 40806439, 2025). "Given the different functionality of RIF1-L and RIF1-S, it is important to understand the expression characteristics and isoform-specific roles of RIF1 in cancer, as such information will help elucidate the role of RIF1 in protecting cancer cells from replication stress." (PMID 40806439, 2025). "Importantly, a significant correlation was found between Rif1 and the regulators of proliferation signalling and maintenance of cancer stem cell characteristics, Wnt/β-catenin." (PMID 37548940, 2024). "Thus, the telomeric function of the Rif1 protein has found application in cancer therapy with satisfactory results, but further research is needed to fully define the function of this protein in tumorigenesis mechanisms." (PMID 37548940, 2024). "RIF1 has recently been demonstrated to contribute to the regulation of stem cell pluripotency, DNA replication regulation and DNA repair pathway, but little is known about the role of RIF1 in cancer progression." (PMID 30237512, 2018). "Considering the complexity of the underlying mechanisms, the role of RIF1 in replication time regulation in human cancer cells requires a large and systematic study, so we did not explore it in this study." (PMID 30237512, 2018). "Since then little is known about the role of RIF1 in cancer progression and chemotherapy response." (PMID 29291010, 2017). "On the other hand, high expression of RIF1 in cancer cells was hypothesized to result in increased DSB repair and confer drug resistance." (PMID 29291010, 2017). "However, little is known about the molecular mechanisms and physiological significance of RIF1 in cancer and chemotherapy efficacy." (PMID 29291010, 2017).
cancer (continued). "We envision that 53BP1 hypo-phosphorylation and ATM inactivation, along with the failure of RIF1 and PTIP foci formation, may emerge as novel indicators for PARPi resistance in BRCA1-mutated cancer patients." (PMID 27462418, 2015). "However, whether the two RIF1 isoforms show differential expression in cancer patients has remained unclear." (PMID 40806439, 2025). "Since RIF1 is reported to be involved in ES self-renewal and is highly expressed in mouse embryonic stem cells (ESCs), we explored whether the expression of RIF1 is related to cancer stem cell-like (CSC-like) traits in EOC cells." (PMID 30075819, 2018). "RIF1 alternative splicing was regulated by a suite of RNA-binding proteins, including serine and arginine rich splicing factor 1 (SRSF1), SRSF3, and SRSF7 whose expression and occupancy on RIF1 pre-mRNA changed in response to DNA damage and in primary cancers." (PMID 41489901, 2025). "Interestingly, also in EOC, Rif1 gene knockout sensitized its cells to drugs (cisplatin) and also platinum-based chemotherapy through inhibition of NER proteins in cancer cells." (PMID 37548940, 2024). "Another cancer-related mechanism of RIF1 is the activation of the Wnt/β-catenin signaling in non-small-cell lung carcinoma mediated by PP1." (PMID 34768871, 2021). "RIF1 knockdown inhibited NSCLC cell growth in vitro and in vivo, whereas overexpression of RIF1 in NSCLC cell lines promoted cell growth, cell cycle progression and cancer stem cell (CSC)-like properties via promoting PP1–AXIN interaction and thereby activating Wnt/β-catenin signaling." (PMID 30237512, 2018). "As Wnt signaling has been considered pivotal for carcinogenesis and the maintenance of cancer cellular stemness of NSCLC, we explored whether RIF1 could enhance cell growth and stem cell-like properties in NSCLC by activating Wnt/β-catenin signaling." (PMID 30237512, 2018). "In addition, the protein expression levels of the genes related to cancer stemness, including NANOG and SOX2 were significantly downregulated in RIF1-knockdown EOC cells and were upregulated in RIF1-overexpressed EOC cells." (PMID 30075819, 2018). "Thus, the effect of RIF1 on telomere length regulation in yeasts is not conserved in mammalian cells and particularly in human cancer cells." (PMID 30075819, 2018).
bacterial infections (1 paper, 2013). "Although Rif1−/− male mice are superficially normal, they succumb to bacterial infections owing to CSR defects comparable in severity to that previously reported for 53BP1-deficient mice." (PMID 23333305, 2013).
infection (1 paper, 2013). The state of being infected such as from the introduction of a foreign agent such as serum, vaccine, antigenic substance or organism. "The propensity of male Rif1−/− mice to succumb to infection, coupled to the fact that 53BP1-deficient mice are immune-compromised due to a severe defect in CSR, prompted us to examine the immune status of Rif1−/− mice." (PMID 23333305, 2013). "Such infections have been reported to affect immune-compromised mice, raising the possibility that RIF1 deficiency might manifest in a suboptimal immune response." (PMID 23333305, 2013). "However, the health of some of the Rif1−/− animals deteriorated rapidly as a result of infections of the commensal bacteria Staphylococcous xylosus." (PMID 23333305, 2013).
RIF1 also shares sentences with these, for which no sentence is quoted: autoimmune disease (1 paper); bone marrow failure (1); breast invasive carcinoma (1); breast tumour (1); clear cell renal cell carcinoma (1); colon adenocarcinoma (1); colon carcinoma (1); colorectal cancer (1); Endometrioid Ovarian Cancer (1); Fanconi anemia (1); hepatocellular carcinoma (1); leukaemia (1); metastatic tumor (1); Mitochondrial myopathy (1); neuroblastoma (1); osteomyelitis (1); osteosarcoma (1); pancreatic cancer (1); serous ovarian cancer (1); thyroid cancer (1); viral infection (1).